TGFB1 (transforming growth factor beta 1)
Diseases named in the same sentence as TGFB1 in open-access papers (continued):
Sharing a sentence is not in itself a finding about the gene and the disease.
Obesity (continued). "Furthermore, obesity-related factors, particularly mechanical stress, contribute to OA development by regulating autophagy and other pathways, such as miR-590-5p or TGFβ1." (PMID 38792546, 2024). "Our study shows a higher expression of OAS1 and TGFB1 in individuals with obesity." (PMID 38731851, 2024). "Furthermore, TGFβ1 has been found to be released from adipose tissue and is elevated in individuals with obesity." (PMID 37626717, 2023). "Similarly, TGFβ1 secretion was found to be greater in the adipose tissue of individuals with obesity when compared to a control group of individuals with normal BMI." (PMID 37626717, 2023). "In addition to stimulating the fibrosis process, recent studies suggest that the TGFβ1/SMAD signal pathway is also implicated in the pathogenesis of metabolic disorders, including obesity and DM." (PMID 36430743, 2022). "These same studies showed a decrease in the activation of latent TGFβ1, both in vitro and in vivo, and indicated that TSP1 deficiency and a decline in latent TGFβ1 activation could be protective against inflammation and obesity." (PMID 33854480, 2021). "Thus, in IBS with diarrhea, especially in its comorbid course with obesity, there is an imbalance of cytokines, which was manifested through a reduced content of IL-10 with increasing levels of TNFα and TGFβ1." (PMID 34621378, 2021). "Since plasma levels of DPT are increased in patients with obesity and considering the contribution of VAT to obesity-associated inflammation and metabolic alterations, we analysed mRNA levels of DPT together with those of TGFB1 in this fat depot." (PMID 32283761, 2020). "In addition, we previously reported that, in an obesity context, TGFβ1 treatment converts human ASCs into myofibroblast-like cells at the expense of adipocyte differentiation." (PMID 28592806, 2017). "This defective TGFβ1 production was confirmed in our second model of obesity, the DIO model." (PMID 20625397, 2010). "Therefore, in addition to defective cytokine production, skin γδ T cells in obesity and metabolic disease were unable to upregulate TGFβ1 production at the wound edge, an important growth factor in several aspects of wound repair." (PMID 20625397, 2010). "Altered TGFβ1 production by skin γδ T cells in obesity and metabolic disease may impact multiple phases of epidermal homeostasis and early and late stages of tissue repair." (PMID 20625397, 2010). "Furthermore, TGFB1 has been implicated in adipose dysfunction under conditions of obesity, evidenced by the reduced expression of adipogenic marker genes (ADIPOQ) in mouse adipocytes treated with TGFB1 and increases in Tgfb expression in adipose tissue of obese mice." (PMID 38998107, 2024). "We postulate that associations of TGFβ1 with adipose tissue and its higher circulating concentrations in individuals with obesity may only apply to states of active inflammation and obesity, and not to individuals with normal BMI." (PMID 37626717, 2023). "In addition, elevated levels of TGFβ1 in lung tissue from lung stromal cells may promote an immunosuppressive phenotype in the recruited macrophages in obesity." (PMID 33670906, 2021). "Patients under 65 years old showed a higher expression of TFRC (p = 0.002), CCL5 (p < 0.001) and IFI6 (p = 0.006), and those with obesity (BMI ≥ 30) presented higher expression of OAS1 (p = 0.008) and TGFB1 (p = 0.008)." (PMID 38731851, 2024). "TGFB1 and FOSL2 are both major transcription factors and closely related to the pathological process of obesity in PCOS." (PMID 36873932, 2023).
Obesity (continued). "In this study, we also observed an increase in TGFβ1 expression in HFD-fed mice, suggesting similar pathways in which TGFβ1 induces CD103+DCs in AT during obesity." (PMID 35456006, 2022). "The highest concentration of TGFβ1 was observed in the group of patients with IBS with diarrhea and obesity (41.7% higher than in almost healthy individuals; 29.5% higher than in patients with diarrhea without obesity)." (PMID 34621378, 2021). "Given that the liver represents a main metabolic organ and that one of the best-recognized hepatic disorders related with obesity is NAFLD, our aim was to investigate the hepatic regulation of DPT and TGFB1 in this condition." (PMID 32283761, 2020). "As for patients with COPD, the Activin A Receptor Type 2B (ACVR2B) and Transforming Growth Factor Beta 1 (TGFβ1), which were the key modulators of BMPR2 pathway, were significantly downregulated, as well as the obesity-related gene Apelin Receptor Early Endogenous Ligand (APELA)." (PMID 37886639, 2023). "In a high-fat diet model of obesity in mice, both decorin and TGFβ1 were significantly enhanced in the ECM surrounding mammary epithelial cells, and complexes of decorin and latent TGFβ1 were identified in ECM isolated from breast tissue from women with obesity." (PMID 35435599, 2022). "As an activator of TGFβ1, TSP-1 could modulate the functions of TGFβ1 in cardiovascular diseases, atherosclerosis, and obesity." (PMID 21765615, 2011). "The adipokines with black lettering are those whose circulating levels are enhanced in obesity and whose total release by adipose tissue explants is enhanced in obesity: IL-6, IL-10, ACE, TGFβ1, ICAM-1, TNFα, IL-1β, PAI-1, and IL-8 that are released by nonfat cells." (PMID 20508843, 2010). "Taken together, these data suggest that HFD induces the IRF3, TGFβ1, and STAT3 signaling pathways in AT that in part might suppress the expression of PPAR-γ to maintain low-grade chronic inflammation in AT during HFD-induced obesity." (PMID 35456006, 2022). "The presence of such regulatory macrophages in obese adipose tissue may be ideal given their secretion of the anti-inflammatory cytokines, IL-10 and TGFβ1, and the lack of antigen presentation to T helper cells that could exacerbate chronic inflammation in obesity." (PMID 24465472, 2014). "Inflammatory adipokines [IL-6, IL-10, ACE, TGFβ1, TNFα, IL-1β, PAI-1, and IL-8] plus one anti-inflammatory [IL-10] adipokine were identified whose circulating levels as well as in vitro release by fat are enhanced in obesity and are primarily released by the nonfat cells of human adipose tissue." (PMID 20508843, 2010).
atherosclerosis (319 papers, 2006 to 2026). A disease characterized by the build-up of fatty material and calcium deposition in the arterial wall resulting in partial or complete occlusion of the arterial lumen. "CELSR2, FN1, SPARCL1, APOE, LPA, APOA5, and TGFB1 exhibit causal associations with both atherosclerosis and four cardiovascular diseases, suggesting their potential as therapeutic targets for atherosclerosis." (PMID 40649979, 2025). "The pathogenesis of atherosclerosis is associated with two major signaling pathways: TGF-β1/Smad2/3 and TGFβ1/TAK1/Nf-κB." (PMID 41154653, 2025). "Aberrant regulation of TGFβ1 signaling underlies the pathogenesis of vascular fibrotic diseases, including atherosclerosis and restenosis." (PMID 29423034, 2018). "Although the role of TGFβ1 in the pathogenesis of atherosclerosis is being recognized, the association between plasma TGFβ1 levels and coronary heart disease (CHD) risk is still controversial." (PMID 22607024, 2012). "Although there is a significant correlation between TGFβ1 and the pathogenesis of atherosclerosis, the relationship between plasma TGFβ1 levels and the risk of ACS remains unclear." (PMID 34239024, 2021). "In early stages of the disease, TGFB1 may be atheroprotective and higher levels of TGFB1 have been reported to decrease the risk of atherosclerosis." (PMID 28829817, 2017). "Our aim here was to investigate the effect of high glucose on the expression of atherogenic genes via TGFβ1/Smad signaling to provide further knowledge on the possible role of high glucose in the development of atherosclerosis." (PMID 39062148, 2024). "TGFB1 has been shown to promote the progression of atherosclerosis by stimulating the conversion of fibroblasts to myofibroblasts and inhibiting endothelial cell proliferation, causing endothelial mesenchymal transition." (PMID 38689297, 2024). "Staining was performed for pSMAD2 as an activation marker of the TGFβ1 canonical signaling pathway which, despite its reparative and anti-inflammatory profile, can also be pro-inflammatory in atherosclerosis when endothelial-derived." (PMID 38693516, 2024). "TGFβ1 levels have been demonstrated to be increased in experimental atherosclerosis, aortic aneurysmal disease, atherosclerotic plaques in patients with coronary hearth disease, and in monocytes circulating in patients with atrial fibrillation and fibrosis." (PMID 39062148, 2024). "In this context, a plethora of studies showed that TGFβ1/Smad signaling pathway played a central role in cardiovascular and cerebrovascular diseases, including atherosclerosis." (PMID 37175608, 2023). "Clinical studies have illustrated that plasma levels of active TGFβ1 are markedly reduced in patients with advanced atherosclerosis compared with healthy controls." (PMID 30227237, 2019). "Particularly, TGFβ1 is involved in the pathogenesis of a range of vascular fibrotic diseases, such as restenosis, atherosclerosis, and hypertension." (PMID 29423034, 2018). "TGFB1 is a very likely CAD candidate gene and has been linked to a range of cardiovascular traits such atherosclerosis, hypertension, inflammation and aneurysm." (PMID 28829817, 2017). "Both of these are known to be associated with lower cholesterol levels and both of TGFβ1 and IL10 are known to inhibit the development of atherosclerosis." (PMID 26187646, 2015). "With our atherosclerosis model we can only study the TGFβ1 side effects of increased cancer and infections with great difficulty." (PMID 25236373, 2014). "This animal study focused on the gene therapy manipulation of the very powerful TGFβ1 signal transduction pathway for inhibiting atherosclerosis, by the delivery of the human SMAD3 gene." (PMID 25236373, 2014).
atherosclerosis (continued). "Unsupervised DEGs analysis of SMCs revealed increased expression in Abcb8ECKO of TGF-β-pathway genes such as Tgfb1, Tgfb2, Tgfb3, Mmp2 and Col1a1, inflammatory genes such as Ccl2 (encoding for MCP1) and Csf1 as well as atherosclerosis-associated genes including Egr1, Sqstm1, Irf1, Sox4 and Xylt1." (PMID 41252867, 2025). "FN1 and TGFB1 have the potential for drug repurposing in atherosclerosis treatment." (PMID 40649979, 2025). "Additionally, one existing drug targeting FN1 and two drugs targeting TGFB1 have the potential for repurposing in atherosclerosis treatment." (PMID 40649979, 2025). "Comparison of top-scored IPA canonical analysis showed that atherosclerosis signaling may relate to interactions between CLU and proteins encoded by congenital toxoplasmosis susceptibility genes (TGFβ1, COL2A1, ALOX12, NFκB1)." (PMID 28904337, 2017). "Notably, FN1 and TGFB1 have approved drugs targeting other diseases, which may be repurposed for atherosclerosis treatment." (PMID 40649979, 2025). "SMC proliferation and lipid peroxide product accumulation-associated indices, including TGFβ-1 and MDA, were also observed in the SMC supernatant, therefore this model can be used to evaluate the effects of drugs, focus-sing on pathological processes associated with atherosclerosis." (PMID 25936371, 2015). "Seven core targets-IFNG, CXCL8, TNF, TGFB1, IL2, IL4, and RELA-were identified via network pharmacology, involving key pathways such as lipid-atherosclerosis, AGE-RAGE, and IL-17 signaling." (PMID 40708520, 2026). "The three most promising proteins (CELSR2, FN1, and SPARCL1) were identified as potential therapeutic targets for atherosclerosis, while APOE, LPA, APOA5, TGFB1, and AGER also hold potential as drug targets for the disease." (PMID 40649979, 2025). "Interestingly, atherosclerosis Treg cells in both PBMC and plaque had increased expression of TGFB1 compared to the PSA Treg cells." (PMID 38665903, 2023). "Many of the genes differentially regulated during monocyte-to-macrophage differentiation (downregulated genes include JAK2, STAT6, TLR8, and TLR2, and upregulated genes include VEGFB, TGFB1, FN1, IL-1R2, SCARB1, MSR1, and CD163) have been previously reported in the pathogenesis of atherosclerosis." (PMID 25011540, 2014). "Many mRNA expressions of adherent and atherosclerosis-related factors were increased but not statistically significant except VCAM-1 and transforming growth factor-beta 1 (TGF-β1) in the adenine rats." (PMID 24829798, 2014).
COVID-19 (316 papers, 2020 to 2026). A disease caused by infection with severe acute respiratory syndrome coronavirus 2. "These conditions are precipitated in part by COVID-19-induced dysregulation of cooperation networks 9 and 7c, leading to excessive TGFβ1 signaling and decreases in mir-132 levels functioning as a suppressor of pro-inflammatory cytokine production." (PMID 41437993, 2025). "The higher serum TGFβ1 concentrations, which increased with the severity of COVID-19, were measured and TGFβ1 levels at hospitalization is distinctive in predicting the severity and development of complications." (PMID 40233022, 2025). "Together, these results show that high EBV seroprevalence and increased TGFβ1 serum levels in MIS-C and severe adult COVID-19 increase susceptibility to EBV reactivation, potentially affecting disease severity." (PMID 40074901, 2025). "As a result, it has been reported that TGFβ1 levels are the main molecule for the pathophysiology of the disease and are a marker that can be used in the early diagnosis of COVID-19 and the course of the disease." (PMID 40233022, 2025). "While a protective effect of OAS1, IRF9, and IFI6 in asymptomatic and mild COVID-19 is confirmed, the role of TGFB1 and CCL5 is still controversial." (PMID 37389217, 2023). "HGF often neutralizes transforming growth factor beta-1 (TGFB1), another cytokine involved in apoptosis, which is expressed at high levels in patients with COVID-19 and has been suggested to affect the patient by immunopathological devices." (PMID 36851766, 2023). "Compared with the healthy individuals, the level of TGFβ1 increased in the plasma of COVID-19 patients during acute infection stage but decreased in COVID-19 survivors 6 months after discharge." (PMID 35288537, 2022). "Other factors, such as hypoxia inducible factor 1 (HIF-1), heme oxygenase (HO), transforming growth factor-beta 1 (TGF-β1), nuclear factor kappa B (NF-κB) have also been reported to play important roles on COVID-19." (PMID 35887687, 2022). "The remaining post-COVID-19 signature shows good agreement with single-cell RNA sequencing data and contains, among others, proteins related to TGFβ signaling, maintenance of the ECM (TGFβ1, BMP-6, MMP1, MMP7), and TNF-signaling (TNFα, TWEAK)." (PMID 36405747, 2022). "This is an important finding because TGFβ1 protein induces chronic fibrosis in the lung, which was reported in COVID-19 infected patients." (PMID 34207861, 2021). "Using bulk RNA-sequencing data from PBMC samples of COVID-19 patients, we also found that TGFB1 expression was significantly decreased in both mild COVID-19 patients and those requiring ICU level care, as compared to non-COVID-19 patients." (PMID 34108016, 2021). "HGF frequently counteracts TGFB1, another cytokine involved in apoptosis, and expressed at elevated levels in COVID-19 patients." (PMID 33239683, 2020). "As SARS-CoV-2 N protein can enhance TGF-β/Smad3 signaling to cause tubular epithelial cell death and AKI via the G1 cell cycle arrest mechanism, the regulation of TGFB1 might be significant in COVID-19 AKI." (PMID 37274117, 2023). "In addition, TGFβ1, TGFβ3, IL-10, and IL-6 were prognostic makers for the early phase of COVID-19 severity, consistent with previous reports." (PMID 37569646, 2023). "Macrophages from patients with IPF and COVID-19 were both found to express fibrosis-associated genes including Secreted Phosphoprotein 1 (SPP1), transforming growth factor beta 1 (TGFB1), transforming growth factor beta-induced (TGFBI), legumain (LGMN), and C-C Motif Chemokine Ligand 18 (CCL18)." (PMID 37759460, 2023). "In addition to decreased expression of genes related to effector function in T cells, we further found an increase of TGFB1 expression in effector COVID-19 patients treated with nasal Foralumab." (PMID 36881624, 2023).